SULT6B1 (sulfotransferase family 6B member 1)
Description:
Sulfotransferase that utilizes 3'-phospho-5'-adenylyl sulfate (PAPS) as sulfonate donor to catalyze the sulfate conjugation of thyroxine. Involved in the metabolism of thyroxine (By similarity).
Synonyms: ST6B1
Tractability: No criterion of Open Targets' tractability assessment is met for any kind of drug.
Gene: Protein-coding gene on chromosome 2 (37,167,820 to 37,196,598, reverse strand). Ensembl gene ENSG00000138068.
Subcellular location: Cytoplasm, cytosol
Pathways (Reactome):
Metabolism: Cytosolic sulfonation of small molecules
Gene Ontology:
Molecular function: sulfotransferase activity
Biological process: sulfation
Cellular component: cytosol
Genetic constraint (gnomAD): Loss-of-function variants: 30 observed, 26.09 expected, observed/expected ratio (o/e) 1.15, 90% interval 0.86 to 1.56. The upper end of that interval is the gene's LOEUF score, 1.56, which puts it in group 6 of 6, group 1 being the genes least tolerant of losing a copy. Missense variants: 330 observed, 280.45 expected, observed/expected ratio (o/e) 1.18, 90% interval 1.08 to 1.29. Synonymous variants: 108 observed, 99.49 expected, observed/expected ratio (o/e) 1.09, 90% interval 0.93 to 1.27.
Homologues: Orthologues: chimpanzee SULT6B1 (98% identical), dog SULT6B1 (91% identical), pig SULT6B1 (87% identical), rabbit SULT6B1 (86% identical), mouse Sult6b1 (85% identical), guinea pig SULT6B1 (84% identical), macaque SULT6B1 (83% identical), rat Sult6b1 (83% identical), tropical clawed frog sult6b1.5 (46% identical), zebrafish sult6b1 (44% identical), tropical clawed frog sult6b1.2 (42% identical), Drosophila melanogaster St1 (23% identical), and 2 more. Paralogues in human: SULT1A1 (30% identical), SULT1A2 (30% identical), SULT1A3 (30% identical), SULT1A4 (30% identical), SULT1B1 (30% identical), SULT1C4 (29% identical), SULT2A1 (29% identical), SULT2B1 (29% identical), SULT1E1 (29% identical), SULT1C2 (28% identical), SULT1C3 (27% identical), SULT4A1 (23% identical).
Diseases named in the same sentence as SULT6B1 in open-access papers:
SULT6B1 is named in the same sentence as 2 diseases in open-access papers, as found by Europe PMC text mining. Sharing a sentence is not in itself a finding about the gene and the disease. The quoted sentences say what the papers report.
autism (1 paper, 2025). Persistent deficits in social interaction and communication and interaction as well as a markedly restricted repertoire of activity and interest as well as repetitive patterns of behavior. "The expression of one with no established function in the brain Sult6b1, one with association to Autism Sema5a, and one with well-established role in the brain Ccl7 was examined." (PMID 38721690, 2025).
schizophrenia (1 paper, 2017). A major psychotic disorder characterized by abnormalities in the perception or expression of reality. "However, meta-analysis of the Japanese samples with 479 cases and 2938 controls from a United Kingdom (UK) schizophrenia GWAS showed that the SULT6B1 SNP (p = 3.7 × 10−5) as well as SNPs in the GIRK2 (rs2787566, p = 0.0014) and NOTCH4 (rs2071287, p = 0.0014) genes were associated with schizophrenia." (PMID 28855529, 2017).